RN7SL566P (RNA, 7SL, cytoplasmic 566, pseudogene)
Gene: Miscellaneous RNA gene on chromosome 19 (39,369,153 to 39,369,448, forward strand). Ensembl gene ENSG00000241983.
Homologues: Orthologues: chimpanzee Metazoa_SRP (99% identical), macaque Metazoa_SRP (94% identical). Paralogues in human: RN7SL1 (88% identical), RN7SL2 (86% identical), RN7SL3 (86% identical), RN7SL788P (85% identical), RN7SL278P (85% identical), RN7SL296P (84% identical), RN7SL220P (84% identical), RN7SL126P (84% identical), RN7SL230P (84% identical), RN7SL14P (83% identical), RN7SL431P (83% identical), RN7SL478P (83% identical), and 703 more.